NOD2 (nucleotide binding oligomerization domain containing 2)
Diseases named in the same sentence as NOD2 in open-access papers (continued):
Sharing a sentence is not in itself a finding about the gene and the disease.
leprosy (continued). "Although the association between NOD2 variants and TB has also been widely investigated, the results of these studies have not reached very consistent conclusions (unlike those for leprosy), which may be related to the high heterogeneity among different Mtb strains." (PMID 41017210, 2025). "In a familial sample from Vietnam including 286 MB and 188 PB leprosy patients (WHO-88), signals located in HLA-DR-DQ, RIPK2, CCDC122, LACC1, and NOD2 were validated (p < 0.05), and the effect was stronger in MB patients for HLA-DR-DQ, CCDC122, and LACC1." (PMID 27219008, 2016). "The absence of functional evidence on NOD2’s role, combined with the inconsistent genetic association findings across different populations, may result from the polygenic inheritance patterns characterising leprosy, warranting further studies to explore this area." (PMID 40435099, 2025). "Moreover, signals of DNase‐seq, H3K4me3 ChIP‐seq, or H3K27ac ChIP‐seq were observed in skin or PBMCs in SNPs among the previously identified known leprosy loci, including loci that EGR2, TNFSF15, RAB32, and NOD2 located in." (PMID 38020709, 2023). "A stepwise association study of leprosy and the non-HLA genes that were significantly associated in the GWAS (RIPK2, TNFSF15, NOD2 and CCDC122-LACC1) was conducted in four independent Brazilian population samples." (PMID 30116885, 2018). "The biological relevance of this pathway was demonstrated in leprosy, in which NOD2, IL-32, and CD1+ DC all were more highly expressed in skin lesions from patients with the self-limited tuberculoid (T-lep) form versus the progressive lepromatous leprosy (L-lep) form." (PMID 27297389, 2016). "IL-32 induction was measured, since it is specific to NOD2 versus TLR2/1 activation and is required to induce CD1b+ DC differentiation and cross-presentation, and its expression at the site of disease correlates with the self-limited versus progressive form of leprosy." (PMID 27297389, 2016). "Finally, we cannot exclude the possibility that NOD2, TNFSF15 and RIPK2 are not true leprosy susceptibility loci." (PMID 20617178, 2010). "Unlike TLR2/1 ligands, MDP acting on NOD2‐activated monocytes is more likely to induce the rapid differentiation of monocytes into CD1+ DCs and to induce MHC‐I‐associated antigen presentation by an IL‐32‐dependent mechanism, which was also confirmed in leprosy lesions." (PMID 41017210, 2025). "Among the genes specific for CD, RIPK2, LACC1, and NOD2 have been shown to be associated in leprosy studies but not specifically with the PB form (NOD2 and RIPK2 with leprosy per se and LACC1 with MB leprosy)." (PMID 27219008, 2016). "Although NOD2 single-nucleotide polymorphisms and NOD2 downstream immune responses are thought to contribute to the pathogenesis of leprosy, it is not clear whether M. leprae, which has a distinct MDP structure, activates the NOD2 pathway." (PMID 27297389, 2016).
Obesity (32 papers, 2014 to 2025). Accumulation of substantial excess body fat. "Despite showing an increase of inflammatory cells in the BAL and lung tissue, we did not observe significant changes in IgE levels and pulmonary edema in NOD2-deficient mice during obesity." (PMID 39507249, 2024). "Still, little is known about the interplay between NOD1 and NOD2 and possible antagonistic effects, and the molecular determinants that are causal for the activation of NOD1 and NOD2 in obesity." (PMID 37239938, 2023). "In experimental models, Nod2 deficiency is associated with increased sensitivity to diet-dependent obesity, steatosis, and hepatic and adipose tissue inflammation." (PMID 33239685, 2020). "In this study, we have identified a novel role for Nod2 and demonstrate that Nod2 protects mice from obesity-associated hepatic carcinogenesis." (PMID 33239685, 2020). "In our previous work, we have demonstrated that Nod2−/− mice are more susceptible than WT mice to diet-dependent obesity and metabolic disease, and that this susceptibility was in part due the Nod2−/− HFD microbiome." (PMID 33239685, 2020). "We report that deletion of the innate immunity antibacterial gene Nod2 abolishes this resistance, as Nod2−/− BALB/c mice developed HFD-dependent obesity and hallmark features of metabolic syndrome." (PMID 28373658, 2017). "Here, we have associated NOD2 with a microbial community that prevents excessive inflammation and insulin resistance during obesity." (PMID 25666722, 2015). "NOD1 and NOD2 can balance pathogenic and protective immune responses during obesity." (PMID 39507249, 2024). "Importantly, CXCL1, S100A8, and NOD2 were also found to be positively associated with obesity in our murine study." (PMID 33123173, 2020). "To unravel the molecular mechanism underlying the development of obesity-dependent liver tumors in Nod2−/− mice in a unbiased manner, we performed RNAseq using total RNA from the livers of male WT and Nod2−/− mice treated with DMBA and maintained on HFD for 31 weeks." (PMID 33239685, 2020). "Since obesity can lead to changes in commensal bacteria populations, intestinal permeability, and translocation of pathogenic bacteria, we investigated the role of NOD2 in the regulation of gut barrier integrity." (PMID 32774333, 2020). "Furthermore, the dysbiosis in mice continually bred with a NOD2-deletion plus the stress of an obesity-causing diet is an independent and transmissible factor that contributes to increased metabolic inflammation and insulin resistance." (PMID 25666722, 2015). "Increased expression of NOD2 has been reported in a range of human metabolic diseases, including obesity, diabetes, nonalcoholic fatty liver disease, and metabolic syndrome." (PMID 40384781, 2025). "NOD2 is a pattern recognition receptor that regulates the host innate immune response and reduces inflammation, inhibiting steatosis and obesity." (PMID 40384781, 2025). "Despite some similar signaling pathways, NOD1 and NOD2 can produce divergent metabolic and immunometabolism outcomes, including regulation of blood glucose and adipose tissue inflammation during obesity." (PMID 39507249, 2024). "Our study describes that NOD1 and NOD2 have distinct roles in allergic lung inflammation during diet-induced obesity." (PMID 39507249, 2024). "Ovalbumin (OVA)-induced lung inflammation was similar in female Nod1−/− and wild-type mice during high-fat-diet-induced obesity, but allergic lung inflammation was higher in obese, high-fat-diet-fed female Nod2−/− mice." (PMID 39507249, 2024). "Obesity reduces lung remodeling during OVA exposure; however, NOD2 attenuates the structural pathological lung changes caused by allergic airway inflammation in female mice since obese NOD2-deficient mice display enhanced tissue damage induced by OVA." (PMID 39507249, 2024).
Obesity (continued). "Yahia (2021) showed that despite a reduction in the number of inflammatory cells in the BAL of both NOD1- and NOD2-deficient lean female mice, only NOD1 affected the respiratory function, which should be considered in future obesity studies." (PMID 39507249, 2024). "We provide evidence that the deletion of NOD2 enhanced lung inflammation and is required for dampening lung inflammation during diet-induced obesity in female mice." (PMID 39507249, 2024). "Of the 22 human NLRs known to date, six proteins (NLRP3, NLRP6, NOD1, NOD2, NLRC5 and NLRP12) have been described to be associated with obesity and low-grade inflammation and one (NLRP3) with postprandial inflammation." (PMID 37239938, 2023). "In vivo experiments confirmed the detrimental role of NOD1 in obesity, as Nod1 and Nod2 double KO mice showed reduced HFD-induced IR, lipid accumulation, adipocyte size and inflammation in liver and AT compared to WT mice on HFD." (PMID 37239938, 2023). "Muramyl dipeptide mitigates obesity-induced insulin resistance by targeting nucleotide-binding oligomerization domain-containing protein 2 (NOD2) and interferon regulatory factor 4 (IRF4)." (PMID 38201117, 2023). "NOD2 acts as a tumor suppressor and was found to protect mice from inflammation and obesity-dependent HCC." (PMID 36304988, 2022). "While NOD1 and NOD2 have been demonstrated to alter systemic metabolic phenotypes (e.g., obesity, insulin sensitivity, etc.), there is also evidence that they play a role in cellular metabolic stress signaling." (PMID 33503814, 2021). "Increased expression of NOD1 and/or NOD2 has been reported in a range of human metabolic diseases, including obesity, diabetes, non-alcoholic fatty liver disease, and metabolic syndrome." (PMID 33503814, 2021). "NOD2 is a pattern recognition receptor that can regulate the host's innate immune response and prevent inflammation, steatosis and obesity." (PMID 34906145, 2021). "We and others have previously demonstrated that the bacterial sensor and innate immunity molecule Nod2 protects from diet-induced obesity, steatosis, and low-level inflammation." (PMID 33239685, 2020). "Our previous and current results demonstrate that the development of obesity and diet-dependent hepatic malignancy in Nod2−/− mice is accompanied by increased expression of many immune response genes in the liver and adipose tissue." (PMID 33239685, 2020). "In summary, our data suggest that NOD2 activation alleviates the insulin resistance, pancreatic dysfunction and restricts the obesity-induced T2D onset." (PMID 32774333, 2020). "Taken together, our data indicate that NOD2 activation limits the adiposity and reduces inflammatory and metabolic defects associated with HFD-induced obesity." (PMID 32774333, 2020). "Nod2 is a pattern recognition receptor that modulates host innate immune responses and protects from inflammation, steatosis, and obesity." (PMID 33239685, 2020). "Overall, we findings showed that NOD2 activation improves glucose and lipid homeostasis and delays the obesity-induced T2D progression." (PMID 32774333, 2020). "In summary, we have discovered that deletion of Nod2 abolishes the resistance of BALB/c mice to HFD-induced obesity and metabolic dysfunction." (PMID 28373658, 2017). "We demonstrate in this study that deletion of the pattern recognition receptor Nod2 abolishes the resistance of BALB/c to HFD-induced obesity." (PMID 28373658, 2017). "We next determined the role of the gut microbiota in diet-dependent obesity in Nod2−/− mice by depleting gut bacteria with antibiotics." (PMID 28373658, 2017). "An obesity-promoting high-fat diet (HFD) increased NOD2 in hepatocytes and adipocytes, and NOD2−/− mice have increased adipose tissue and liver inflammation and exacerbated insulin resistance during a HFD." (PMID 25666722, 2015).
Obesity (continued). "MDP-based postbiotics via NOD2 act as insulin sensitizers, as indicated by reduced adipose tissue inflammation and reduced glucose intolerance in mice with obesity without the alteration of gut microbiota and weight loss." (PMID 40592472, 2025). "Nucleotide-binding oligomerization domain 1 (NOD1) or NOD-like Receptor pyrin domain containing 3 (NLRP3) activation promote metabolic inflammation and insulin resistance while NOD2 activation improves insulin sensitivity and glucose homeostasis during obesity." (PMID 41853552, 2024). "For example, obesity has been linked with methylation changes in genes involved in lipid metabolism (ABCG1, SREBF1, and NOD2), which may explain the comorbidities noted in obesity." (PMID 36656735, 2023). "This shows a reciprocal influence of NOD2, the microbiota and the metabolism in obesity." (PMID 37239938, 2023). "Based on these differences, NOD1 inhibition might serve as a therapeutic option to alleviate obesity-induced glucose intolerance, while NOD2 stimulation might favor blood glucose homeostasis." (PMID 37239938, 2023). "The higher NOD2 expression in patients with obesity likely indicates heightened surveillance to bacteria, as this receptor recognizes fragments of bacterial peptidoglycan, such as muramyl dipeptide, and this is relevant in complicated infections where bacteria are involved." (PMID 35837843, 2022). "Increased expression of NOD1 and/or NOD2 has been reported in a range of human metabolic diseases, including obesity, diabetes, non-alcoholic fatty liver disease (NAFLD), and metabolic syndrome, or chronic diseases associated with mitochondrial dysfunction, such as IBD." (PMID 33503814, 2021). "Additionally, a major gap in our understanding is the opposing roles NOD1 and NOD2 play in the control of diet-induced obesity and insulin resistance." (PMID 33503814, 2021). "Overall, NOD2 activation is required for a protective Th17 over Th1 immunity in the gut, which seems to decrease gram-negative bacteria outgrowth in gut microbiota, attenuating the endotoxemia, metainflammation, and protecting against obesity-induced T2D." (PMID 32774333, 2020). "These pathologies are risk factors for hepatocellular carcinoma, however, the role of Nod2 in obesity-associated liver malignancy was not known." (PMID 33239685, 2020). "A second parallel mechanism that may contribute to the development of diet-dependent obesity and hepatic malignancy in Nod2−/− mice may be the recently described Nod2-mediated activation of AMPK24." (PMID 33239685, 2020). "Obesity and inflammation are risk factors for hepatocellular carcinoma, however, the role of Nod2 in obesity-dependent hepatic tumorigenesis is not known." (PMID 33239685, 2020). "Obesity has been associated with increased expression levels of NOD2 in hepatocytes; however, the exact role of NOD2 in obesity remains unknown." (PMID 30134638, 2018). "However there is no previous evidence for the role of the innate immunity gene Nod2 in regulating sensitivity to obesity." (PMID 28373658, 2017). "Thus, our data demonstrate that in WT mice Nod2 protects from the development of HFD-induced obesity and that Nod2 deletion reverses the resistance to obesity observed in WT BALB/c mice." (PMID 28373658, 2017). "CRC is related to environmental factors (e.g., smoking, diet, obesity, alcohol), immune system dysregulation, or genetics, such as mutations of microsatellite instability (MSI) genes MSH1, MLH1, and MSH6, adenomatous polyposis coli (APC), or nucleotide-binding oligomerization domain 2 (NOD2)." (PMID 40376304, 2025). "Interestingly, a similar pattern of lower expression of many inflammatory markers occurred in both male WTfl/fl and male AdipoIRF4fl/fl mice after MDP treatment, despite male AdipoIRF4fl/fl mice being refractory to NOD2‐mediated glucose changes during low‐level endotoxemia and during obesity." (PMID 35993451, 2022).
Obesity (continued). "To test our hypothesis that development of diet-dependent obesity in Nod2−/− mice increases sensitivity to liver cancer, we treated WT and Nod2−/− 4–5 day old pups one-time with the carcinogen dimethylbenz[a]anthracene (DMBA) and 3 days later placed their nursing mothers on HFD." (PMID 33239685, 2020). "The development of obesity and metabolic dysfunction in Nod2−/− mice on HFD has many similarities to the development of HFD-induced pathology in humans, which makes Nod2−/− BALB/c mice a relevant model for the study of HFD-induced obesity and associated diseases." (PMID 28373658, 2017). "In vivo studies have reported that NOD2 stimulation by MDP improves insulin sensitivity, enhances glucose tolerance, and prevents obesity." (PMID 41340462, 2025). "NOD1-mediated insulin resistance and obesity are negatively regulated by IRF4, which is induced by the activation of NOD2 with MDP." (PMID 36268029, 2022). "Additionally, the muramyl dipeptide from bacterial cell wall was a beneficial postbiotic which could mitigate obesity-induced insulin resistance by targeting nucleotide-binding oligomerization domain-containing protein 2 (NOD2) and interferon regulatory factor 4 (IRF4)." (PMID 34579087, 2021). "In summary, we have identified a novel role for Nod2 in obesity and demonstrate that Nod2 and Nod2-regulated microbiota protect BALB/c mice from diet-induced obesity and metabolic dysfunction." (PMID 28373658, 2017). "Our results add NOD2 as an important PRR to the growing list of immune components that protect against dysbiosis and metabolic disease during obesity, which includes TLR2, TLR5, and inflammasome components." (PMID 25666722, 2015). "NOD2 in non-hematopoietic cells protected mice from obesity-induced metabolic inflammation and insulin resistance by limiting bacterial infiltration into metabolic tissues." (PMID 39507249, 2024). "Therefore, NOD1 and NOD2 can have opposing roles in aspects of inflammatory lung disease, but it was not clear if NOD1 or NOD2 influenced the protective effect of obesity on allergenic lung inflammation." (PMID 39507249, 2024). "NOD2 activation after injection of MDP promotes immune tolerance, lowers adipose tissue inflammation, and improves blood glucose control during low‐dose endotoxin challenge and during obesity." (PMID 35993451, 2022). "Although HSCs with SASP play pivotal roles in obesity-dependent hepatocarcinogenesis, the effects of NOD2 activation on HSCs have not yet been explored." (PMID 36268029, 2022). "In this context, we observed that mice lacking NOD2 fed a high-fat diet (HFD) display severe obesity, exhibit greater adiposity, and more hepatic steatosis compared to HFD-fed wild-type (WT) mice." (PMID 32774333, 2020). "It is not yet clear if Nod1 or Nod2 immunometabolism is more important in glucose control during obesity." (PMID 28484277, 2017). "NOD2 sensing of bacterial PGN provides protection from metabolic defects and reinforces that immune proteins can control bacterial homeostasis, which can contribute to insulin resistance and diabetes during high-fat feeding and obesity." (PMID 25666722, 2015). "Intriguingly, augmented obesity beyond that often seen in WT HFD-fed mice was not required for worse glucose tolerance in the absence of NOD2." (PMID 25666722, 2015). "Studies have shown that mice lacking NOD2 appeared hyperglycemia, adipose tissue and liver inflammation under high-fat diet conditions, demonstrating that the NOD2-regulated microbiota can alleviate diet-induced obesity and metabolic dysfunction in mice." (PMID 40384781, 2025). "This has fostered the concept that NOD2 may provide immune tolerization effects to dampen inflammation, but still, it is not clear how NOD1 or NOD2 influences allergic lung inflammation during obesity." (PMID 39507249, 2024). "In the current study, we tested the hypothesis that increased obesity in the absence of Nod2 would result in increased tumorigenesis." (PMID 33239685, 2020).